SNHG14 (small nucleolar RNA host gene 14)
Diseases named in the same sentence as SNHG14 in open-access papers (continued):
Sharing a sentence is not in itself a finding about the gene and the disease.
tumor (continued). "In the SNHG14 knockdown group, reduced tumour volume was observed at 28, 35 and 42 days after cell injections compared." (PMID 31513352, 2019). "Through in animal experiments, we suggested that SNHG14 promoted tumor growth of DLBCL through regulating the PD-1/PD-L1 immune checkpoint." (PMID 31570691, 2019). "The tumor volume and weight were increased by SNHG14 overexpression whereas were decreased by anti-PD-L1, and anti-PD-L1 reversed the increase of tumor volume and weight caused by SNHG14 overexpression." (PMID 31570691, 2019). "As expected, SNHG14 abrogated the trastuzumab‐induced growth suppression of xenograft tumour, indicating that SNHG14 promotes trastuzumab resistance in our mice models." (PMID 30063126, 2018). "Furthermore, metastasis experiments were conducted in mice in vivo, suggesting that, compared to the control group, secondary tumours metastasising to the liver were diminished in the SNHG14 knockdown group." (PMID 40521987, 2025). "In addition to its role in cancer progression, SNHG14 has been identified as a key regulator of immune responses within the tumor microenvironment, functioning as a microRNA sponge and impacting immune cell behavior." (PMID 37760852, 2023). "Lastly, small nucleolar RNA host gene 14 (SNHG14) and plasmacytoma variant translocation 1 (PVT1), two other lncRNAs that promote tumor aggressiveness and lower OS (p < 0.001 and p < 0.032), respectively, were reported to act by sponging, respectively, the miRNAs miR-124 and miR-488-3p." (PMID 35432447, 2022). "The expression level of this lncRNA correlates with cancer cell proliferation, migration, and the overall aggressiveness of the tumor and, according to a review by Shen and colleagues, with higher levels of the SNHG14 expression promoting the aggressiveness of cancer." (PMID 36672838, 2022). "However, the lncRNAs reported in our study share less than 30% TTI with Snhg14, which is overexpressed in several cancers and potentiates tumor progression, in humans, by serving as a sponge (endogenous competitor RNA) for multiple microRNAs." (PMID 34597331, 2021). "Consistent with our in vitro observations, knocking down of SNHG14 resulted in significant decrease of tumor volume and tumor weight; while the overexpression of SSR2 could partially restore the inhibitor effects of shSNHG14." (PMID 33485374, 2021). "Collectively, we could conclude that SNHG14 exerted its tumor-promoting effects through miR876-5p/SSR2 axis in a ceRNA model." (PMID 33485374, 2021). "Finally, in vivo experiments further indicated that down-regulated SNHG14 greatly inhibited CRC tumor growth." (PMID 34234865, 2021). "These in vivo data imply that SNHG14/PABPC1 promotes tumor progression via PTEN signaling in vivo." (PMID 32811821, 2020). "In vivo studies showed that SNHG14 knockdown attenuated tumour growth." (PMID 31513352, 2019). "Furthermore, the expression levels of SNHG14 in the 29 tumor samples were stratified using three types of clinicopathological parameters (gender, age and WHO grade)." (PMID 29552296, 2018). "The most obvious finding to emerge from the analysis was that decreased SNHG14 inhibited proliferation, migration, cell cycle entry and colony formation, and invasion abilities, and facilitated apoptosis of BCa cells, along with reduced the tumor volume and weight of nude mice with BCa." (PMID 33482820, 2021). "In addition, in vivo studies indicated that SNHG14 knockdown exerted anti‐tumour effects." (PMID 31513352, 2019). "small nucleolar RNA host gene 14 (SNHG14) was found to enhance the proliferation, invasion, EMT, and tumor growth of Diffuse large B cell lymphoma (DLBCL)." (PMID 38462628, 2024). "Given the observed dysregulation of SNHG14 in CRC, its involvement in tumor–stroma immune interactions via extracellular vesicles and/or exosomes is suggested, which underscores its relevance in immunity, inflammation, and tumor–stroma immune interplay." (PMID 37760852, 2023).
tumor (continued). "SNHG14, AFAP1-AS1, AGAP2-AS1, and BCRT1 have been proven to be carried by tumor-derived EVs in order to induce trastuzumab resistance in BC cells." (PMID 37629204, 2023). "The lncRNAs interaction with PDCDs is mainly assessed in the context of neoplasia indicating the role of MALAT1, MEG3, SNHG14 and LINC00473 in this process." (PMID 35402235, 2022). "RT-qPCR and western blot analysis showed that SNHG14 and ESM1 levels in the tumor group were apparently increased, and miR-211-3p level was obviously decreased in contrast with the normal group (all P < 0.05)." (PMID 33482820, 2021). "Their data showed that SNHG14 and the autophagy protein ATG14 were upregulated in CRC tumour tissues when compared to normal ones, while miR-186 is downregulated." (PMID 33807355, 2021). "Hence, we used StarBase analysis to predict the potential miRNA, which interacted with SNHG14, and finally selected miR-519b-3p as a potential target, since its dual functions as either oncogene or tumor suppressor in the regulation of the proliferation, migration and apoptosis of tumor cells." (PMID 34234865, 2021). "Among the others, cells depleted of Lin28A and SNHG14 and overexpressing IRF6 had the smallest tumor volumes." (PMID 32527996, 2020). "We observed that silencing of SNHG14 induced a remarkable reduction in tumor size, while overexpression of PABPC1 impaired the suppression of SNHG14 knockdown on tumor growth." (PMID 32811821, 2020). "The overexpression of SNHG14 facilitated, whereas the use of anti-PD-L1 retarded the DLBCL tumor growth in mice, and anti-PD-L1 abrogated the facilitative effect of SNHG14 overexpression on tumor growth." (PMID 31570691, 2019). "Our study firstly uncovered that SNHG14 promoted proliferation, invasion, EMT and tumor growth of DLBCL in vitro and in vivo." (PMID 31570691, 2019). "This in vivo study showed that silencing of SNHG14 increased the miR‐613 expression level, which subsequently down‐regulated ANXA2 expression and suppressed tumour growth." (PMID 31513352, 2019). "More importantly, with treatment of trastuzumab, tumour cells that infected with Lv‐SNHG14 grew faster than controls (Group III vs Group IV), suggesting that SNHG14 repressed the cell cytotoxicity induced by treatment with trastuzumab in vivo." (PMID 30063126, 2018). "Interestingly, wo found that XIST, SNHG14, NEAT1, LINC00943, KCNQ1OT1 have pro-tumor functions in various cancers but DHRS4-AS1 can inhibit tumor development." (PMID 40015977, 2025). "SNHG14 exhibits oncogenic properties in CRC, and DLEU1 demonstrates tumor suppressive functions." (PMID 41378121, 2025). "Targeting the ncRNAs involved in this axis, such as AC008555.6, AC026356.1, TRHDE-AS1, or SNHG14, could potentially disrupt the regulatory mechanisms that lead to PLAUR overexpression, thereby reducing tumor progression and improving patient outcomes." (PMID 40561678, 2025). "For instance, knockdown or overexpression experiments of SNHG14, hsa-miR-340-5p, and PLAUR in NSCLC cell lines could elucidate their regulatory roles in tumor progression and immune cell infiltration." (PMID 40561678, 2025). "SNHG14 and LINC00663 interact with EBF1 to enhance its protein stability and functional activity, whereas LINC00844 recruits EBF1 to the GSTP1 promoter to promote its transcription and exert anti-tumor effects." (PMID 40508012, 2025). "SNHG14 is a long noncoding RNA which in A549 cells suppresses the microRNA, miR-34a, a negative regulator of high mobility group box 1 (HMGB1) mRNA, whose increased expression can promote anti-tumor drug resistance." (PMID 33302475, 2020). "Besides, SNHG14 contributed to CRC cell proliferation, motility and EMT in vitro, and inhibition of it confined CRC tumor growth and liver metastasis in vivo." (PMID 31273190, 2019).
tumor (continued). "They found that in diffuse large B lymphoma, increased expression of lnc-SNHG14 could promote ZEB1 expression through sponge adsorption of miR-5590-3p and further activate PD-L1 and inhibit CD8+ T cells to promote the immune escape of tumor cells." (PMID 33194692, 2020). "This SNHG14/EBF1/FAM171A1 signaling axis has been shown to transform normal fibroblasts (NFs) into pro-tumorigenic CAFs, thereby fostering a microenvironment that supports tumor growth and metastasis." (PMID 40508012, 2025).
cancer (36 papers, 2018 to 2026). A tumor composed of atypical neoplastic, often pleomorphic cells that invade other tissues. "Despite the established oncogenic function of SNHG14 in various human cancers, the underlying mechanism in GC remains elusive." (PMID 40521987, 2025). "In cancer research, several research findings have established that SNHG14 is closely associated with the malignant behaviours of cancer cells, mainly playing a non‐negligible role in enhancing their migration and invasion." (PMID 40521987, 2025). "This review will focus on the SNHG14 gene, its expression patterns, its role in human cancer, and the possibility that single nucleotide variants within the locus contribute to human phenotypes in the general population." (PMID 36672838, 2022). "Functionally, gain- and loss-of-function of SNHG14 revealed that overexpressed SNHG14 promoted cancer cell viability, invasion, and migration, whereas its down-regulation produced the opposite effect." (PMID 34631721, 2021). "SNHG14 could function as an oncogene in cancer progression, even though gemcitabine resistance-associated mechanisms in PDAC remain poorly known." (PMID 36558998, 2022). "Mechanism underlying the function of SNHG14 in various cancers." (PMID 34631721, 2021). "Moreover, SNHG14 is associated with immunity and could be a promising target for the immunotherapy through PD-L1/PD-1 blockade in cancers." (PMID 33552958, 2020). "Small Nucleolar RNA Host Gene 14 (SNHG14) is a novel long non-coding RNA (lncRNA) located on chromosome 15q11.2 that plays a crucial role in the initiation and progression of various malignant tumors." (PMID 41234719, 2025). "Compared with para‐carcinoma tissues, SNHG14 was upregulated in GC tissues, correlating with a poor prognosis in GC patients." (PMID 40521987, 2025). "Small nucleolar RNA host gene 14 (SNHG14) plays a pivotal role in the carcinogenesis of several malignant tumors, such as BC, by regulating cell proliferation, migration, invasion, and chemoresistance." (PMID 39148900, 2024). "SNHG14, an oncogenic marker for lung and pancreatic cancer cells, promotes cell proliferation by sponging miR-340-5p and miR-101-3p, respectively." (PMID 37190145, 2023). "For example, the small nucleolar RNA host gene 14 (SNHG14) plays a role in cancer development in various cancer types and is highly expressed in PDAC compared to normal tissue." (PMID 35740481, 2022). "Specifically, SNHG14 expression was found elevated in breast cancer cells and tissues and its silencing attenuated cancer cell proliferation, migration, and invasion while at the same time enhancing apoptosis." (PMID 36139687, 2022). "Consistent with the results in TCGA, the expression of SNHG14 was higher in cancer tissues (P < 0.001)." (PMID 33485374, 2021). "Small nucleolar RNA host gene 14 (SNHG14) is a long non-coding RNA found to be overexpressed in various types of cancers." (PMID 34631721, 2021). "In this review, we discuss the expression profile, biological function, and molecular mechanisms of SNHG14 in cancers to provide a molecular basis for the clinical utility of SNHG14 in the future." (PMID 34631721, 2021). "It is reported that lncRNA SNHG14 (SNHG14) promotes cell proliferation and invasion in many cancers." (PMID 34234865, 2021). "For instance, the expression of SNHG14 in FHC cell lines is higher than other cancer cells but is lower in NCM460 cell lines." (PMID 33552958, 2020). "Several studies have demonstrated that SNHG14 functions as oncogene in various cancers; however, the biological function of SNHG14 in HCC remains largely elusive." (PMID 32811821, 2020). "Studies over the past two decades have provided important information on the role of SNHG14 in various cancers." (PMID 32912324, 2020). "Small nucleolar RNA host gene 14 (SNHG14) in particular has a role in promoting cancer progression in several cancer types, and is expressed more highly in PDAC compared to normal tissue." (PMID 31905604, 2019).
cancer (continued). "In addition, lncRNA small nucleolar RNA host gene 14 (SNHG14) is often highly expressed in a variety of cancers, leading to poor progression; in CRC, SNHG14 suppresses miR-186 to upregulate ATG14, inducing autophagy in SW620 and SW480 human CRC cells." (PMID 36172152, 2022). "In the following sections, we focus on the function of SNHG14 in various cancers." (PMID 34631721, 2021). "All in all, knocking down SNHG14 is an approach to hinder malignant phenotype of cancer cells." (PMID 33482820, 2021). "The results indicate that SNHG14 can become a prognostic indicator of cancers." (PMID 34631721, 2021). "In this study, we summarize the latest evidence of SNHG14 in human cancers, especially its abnormal expression, biological functions, and molecular mechanisms, and discuss the potential clinical value of SNHG14 as a novel method for cancer diagnosis, prognosis, and treatment." (PMID 34631721, 2021). "SNHG14 exerts oncogenic functions in these cancers and promotes the progression of cancers." (PMID 32912324, 2020). "LncRNA small nucleolar RNA host gene 14 (SNHG14) functions as an oncogene in a variety of cancers." (PMID 32811821, 2020). "Furthermore, interfering with SNHG14 suppresses cancer cell proliferation and promotes apoptosis." (PMID 41234719, 2025). "However, whether the level of SNHG14 is related to the prognosis of patients with different cancer types is unclear." (PMID 36276965, 2022). "Particularly, the small nucleolar RNA host gene 14 (SNHG14) is expressed more strongly in PDAC compared with normal tissue and plays a role in the advancement of numerous cancer types." (PMID 41151762, 2025). "By analyzing scRNA-seq data from 486 cancer cells across subtypes, we identified multiple SNPs in imprinted genes, including HM13, MEST (PEG1), SNHG14 and PEG10, showing consistent biallelic expression." (PMID 39766305, 2024). "One such lncRNA, namely, small nucleolar RNA host gene 14 (SNHG14), is noted to play biological roles in cancers, inflammation, and organ damage." (PMID 36644009, 2023). "Thus, SNHG14 might be a promising prognostic biomarker and therapeutic target for cancers." (PMID 34631721, 2021). "Further, we analyzed the expression of SNHG14 in HCC tissues with different grades, and the expression of SNHG14 was higher in carcinoma tissues with high grade (G3/G4) (P < 0.001)." (PMID 33485374, 2021). "Additionally, SNHG14 enhances malignancy by upregulating STAT3 and increasing the proliferation and invasion of cancer cells through the downregulation of miR-613." (PMID 37760852, 2023). "SNHG14 RNA is overexpressed in multiple cancer types, including non-small cell lung cancer, hepatocellular carcinoma, glioma, breast cancer, ovarian cancer, and colorectal cancer, among others." (PMID 36672838, 2022). "Among them, aberrant expression of SNHG14 and SNHG15 have been discovered in cancers, expression of LINC00667 was proved as a biomarker to predict relapse free survival in patients with small hepatocellular carcinoma, most recently, the roles of VLDLR-AS1 and TNRC6C-AS1 in PTC have been studied." (PMID 31372094, 2019). "Thus, the function of SNHG14 is complicated and might serve as both positive and negative roles in cancer initiation and progression corresponding to bio-context." (PMID 33552958, 2020). "As SNHG14 overexpression in cancer can increase cellular proliferation and migration, it is possible that reduced cell bodies (gray matter) or axons (white matter) in some areas of the brain could be directly due to lack of SNHG14 expression in patients with PWS." (PMID 36672838, 2022).
neurological disease (2 papers, 2019 to 2024). "Previous studies found that SNHG14, as a lncRNA, plays an important role in neurological disease, whereas SNHG14 knockdown reduces neurotoxicity." (PMID 38807051, 2024).
SNHG14 also shares sentences with these, for which no sentence is quoted: retinoblastoma (4 papers); acute lung injury (2); endometrial cancer (2); lung adenocarcinoma (2); acute kidney injury (1); asthma (1); colon cancer (1); diabetes- (1); genetic disorder (1); glioblastoma (1); gynecological cancers (1); hypertrophy (1); Intellectual disability (1); liver cancer (1); lung carcinoma (1); lymphoma (1); malignant glioma (1); melanoma (1); neurodevelopmental disorder (1); psychosis (1).